STAT3 (signal transducer and activator of transcription 3)
Diseases named in the same sentence as STAT3 in open-access papers (continued):
Sharing a sentence is not in itself a finding about the gene and the disease.
melanoma (continued). "Thus, we sought to determine whether BET inhibitors can suppress STAT3 signaling to sensitize melanoma cells to sunitinib." (PMID 36720918, 2023). "Therefore, it is suggested that apigenin could inhibit carcinogenesis by inducing apoptosis in melanoma cells and downregulating the activities of some important survival factors, such as STAT3, Akt, and MAPK proteins." (PMID 36675015, 2023). "Furthermore, we generated STAT3 knockdown melanoma cells by transduction of two different shRNAs and found that STAT3 inhibition significantly enhanced melanoma cell sensitivity to sunitinib." (PMID 36720918, 2023). "Moreover, in the pathogenesis of melanoma, the oncogenic function of BRAFV600E mutation determines constitutive activation of the MEK/ERK pathway in 1205Lu cells, and the MEK/ERK pathway is responsible for STAT3 S727 phosphorylation." (PMID 36672229, 2023). "Therefore, the authors hypothesized that KIF22 might affect the proliferation and glycolysis of melanoma cells by regulating EGFR/STAT3 signaling." (PMID 37944197, 2023). "Therefore, we focused on the LIF/LIFR axis and demonstrated (in three out or four MBM cell lines used in this study) that microglial LIFR activation by LIF in melanoma-exposed microglia induces downstream signaling of the JAK/STAT3 pathway, leading to JunB upregulation." (PMID 37894348, 2023). "Therefore, the STAT3 pathway may mediate the FLU inhibition of PD-1 and MDSC in melanoma, which is further proven by using the STAT3 inhibitor." (PMID 35008943, 2022). "We investigated whether STAT3 can regulate glycolysis metabolism in melanoma cells." (PMID 36188586, 2022). "Notably, STAT3 silencing strongly inhibits the tumor growth in a mouse melanoma model." (PMID 35742999, 2022). "Such an effect might be related to the decreased expression of several CSC genes such as Lats1, Stat3, and Foxp1 in the ALDHhigh cells (data not shown) reported to be associated with melanoma aggressiveness." (PMID 35408953, 2022). "Therefore, STAT3 is a potential target for melanoma immunotherapy." (PMID 34806028, 2021). "Thus, our data raise the possibility that CD27-AS1-208 could be employed as a target for inhibition of STAT3 signaling for melanoma treatment." (PMID 35096622, 2021). "Thus, inhibiting STAT3 may demonstrate an excellent activity on the downregulation of Tim-3, increasing the immune activities in melanoma." (PMID 33936081, 2021). "Therefore, it is plausible that inhibition of IL6/ STAT3 pathway by elevated S100B in melanoma cells could be beneficial to early stage tumors as a way to prevent anti-proliferative effects of IL6 and to avoid immune-related destruction." (PMID 34411141, 2021). "Moreover, blocking AKT or STAT3 pathway with a specific inhibitor could partially reverse the promotion of melanoma malignancy mediated by TRIM14 overexpression." (PMID 33982666, 2021). "Our results presented that pretreated melanoma cells with AKT or STAT3 pathway-specific inhibitor could partially reverse TRIM14 induced tumor cell proliferation, clone formation capacity, invasion, epithelial-mesenchymal transition as well as melanin synthesis capacity." (PMID 33982666, 2021). "Also, we identified that the transient small-molecule reticence of the STAT3 pathway may dramatically expand the usefulness of anti-PD-1 within melanoma." (PMID 33936081, 2021). "Interestingly, STAT3 depletion and anti-PD-1 therapy decreased the percentages of CD8+ and CD4+T cells, leading to an increased CD8/CD4 ratio in STAT3 downregulation and PD-1 blockade combinational treatment in melanoma according to monitoring mice in the PD-1 blockade group." (PMID 33936081, 2021). "Thus, we sought to assess whether tumor-derived IL-1β induces the IL-6/STAT3 signaling axis in melanoma cells." (PMID 34531850, 2021). "Targeting STAT3 via intervening lncRNAs may be of great therapeutic value for melanoma therapy." (PMID 35096622, 2021). "Therefore, targeting STAT3 is a promising strategy for melanoma treatment." (PMID 35096622, 2021).
melanoma (continued). "Importantly, SOX2 expression in melanoma is up-regulated by STAT3 activity." (PMID 32899370, 2020). "Therefore, we could conclude that the inhibitory effect of ATF3-overexpressing HDFs on melanoma cell growth and migration is mainly through the IL-6/STAT3 pathway." (PMID 32373541, 2020). "In addition to MYD88 and TRIF, other molecules might be involved in the signaling cascades from TLR4 to STAT3 in melanoma." (PMID 32312954, 2020). "In addition to its role in inhibiting drug resistance, apigenin reduced cell migration and invasion in the melanoma A375 cell line by decreasing STAT3 phosphorylation, nuclear localization and transcriptional activity, in addition to STAT3 target genes, MMP2, MMP9, VEGF and TWIST1." (PMID 32731620, 2020). "We and others have implicated the transcription factor Stat3 in the progression of cachexia in several experimental models, including the C26 allograft, C26 LM and Apcmin/ + CRC models, as well as the Lewis Lung Carcinoma, B16 melanoma, and ES‐2 ovarian cancer models." (PMID 33200567, 2020). "In summary, we concluded that Lj-1-60 inhibited melanoma proliferation and induced cell cycle arrest into the G2/M phase and apoptosis by targeting Fyn/Stat3 pathway, indicating Lj-1-60 is a potential therapeutic chemical that could be used in the treatment of melanoma." (PMID 32565740, 2020). "No mutation of MYD88, TRIF and STAT3 genes has been reported in melanoma patients." (PMID 32312954, 2020). "Therefore, it is not surprising that STAT3, being a point of convergence of many of these signaling pathways, has been found to be activated at high frequency and has been implicated in melanoma progression." (PMID 30622697, 2019). "Therefore, our hypothesis is that the STAT3 inhibition could also mediate the inhibition of melanoma proliferation and metastatic dissemination that we showed in treated melanoma cells." (PMID 31801187, 2019). "In a mouse model of melanoma, it was further demonstrated that silencing STAT3 in the myeloid and B cells of the tumour microenvironment could circumvent the immunosuppressive effects of STAT3 and achieve clearance of the malignant cells." (PMID 31130718, 2019). "We thus hypothesized that STAT3 might play a role in NDV/FMW-induced ICD in melanoma cells." (PMID 31192135, 2019). "Moreover, just like other known STAT3 inhibitors, compound 1 also interacted with Arg609, an essential amino acid for STAT3 function, suggesting its anti-melanoma activity may well be through inhibition of STAT3, in agreement with the experimental results." (PMID 30691132, 2019). "Notably, C188-9 treatment reduced the protein levels of NDV protein HN in infected melanoma cells, indicating that STAT3 inhibition might decrease NDV/FMW replication in melanoma cells." (PMID 31192135, 2019). "Moreover, ablating STAT3 in myeloid cells increases CpG-induced DCs maturation, T-cell activation, tumor antigen-specific T-cells generation and long-lasting antitumor immunity in B16 melanoma tumor model." (PMID 31480382, 2019). "Furthermore, inhibition of STAT3 signaling led to apoptosis of melanoma cells." (PMID 30691132, 2019). "In invasive melanoma cells, cytokine signaling-induced activation of the JAK1/STAT3 pathway leads to increased ROCK-dependent actomyosin contractility, that feeds back to reinforce STAT3 signaling and promote ECM remodeling by tumor-associated stromal fibroblasts." (PMID 29541636, 2018). "In human melanoma cell lines and primary cultures, curcumin, the primary bioactive component isolated from turmeric and used as dietary spice, induces apoptosis and modulates cellular responses to immunotherapeutic cytokines by suppressing STAT3 phosphorylation." (PMID 30166456, 2018). "Furthermore, since STAT3-KD GICs still produced tumors, our results indicate that the Y705F-STAT3 mutant has a dominant-negative activity in GIC tumorigenesis, which is in agreement with our finding that the Y705F-STAT3 mutant has dominant-negative activity in melanoma." (PMID 29774125, 2018).
melanoma (continued). "Furthermore, MTT assays showed that the cytotoxic effect of SLE could be observed in various melanoma cell lines with different genetic backgrounds, and the effect on p-STAT3-positive cells was stronger than on p-STAT3-negative cells." (PMID 28596565, 2017). "Thus, our results indicating significant basal activation of JAK2, SRC, STATs 1, 3, and 5, in melanoma aids in resolving finer aspects of STAT1 vs. STAT3 as well as acts as a springboard for dissecting studies on cytokine-induced STAT mediated cross-talks between JAK and SRC pathways." (PMID 28223541, 2017). "Our findings demonstrate that the amentoflavone analogue compound 1 is a potent inhibitor of the JAK2/STAT3 signaling pathway against melanoma cells, suggesting that this natural product scaffold could deserve further attention for the development of anti-melanoma therapeutics." (PMID 28570563, 2017). "Additionally, recombinant Erdr1 treatment reduced STAT3 activity in melanoma cell line." (PMID 27941650, 2016). "Next, we examined whether FAD104 colocalized with STAT3 in melanoma cells." (PMID 25671570, 2015). "Therefore, we assessed whether FAD104 interacted with STAT3 in melanoma cells under physiological conditions." (PMID 25671570, 2015). "Furthermore, STAT3 regulates the expression of mmp2 in melanoma cells." (PMID 25671570, 2015). "Therefore knockdown of LIFr may reduce melanoma cell migration via inhibition of STAT3, partly involving p38." (PMID 26329521, 2015). "Moreover, dominant negative STAT3 attenuates the potency of invasion and metastasis of melanoma." (PMID 25671570, 2015). "Indeed, STAT3 is considered to be a key mediator in melanoma which promotes brain metastasis." (PMID 25101298, 2014). "Similarly, IL-6 mediated growth arrest in melanoma is STAT3-dependent." (PMID 24518612, 2014). "Furthermore, sensitivity of MEK-inhibitor-resistant melanoma cell lines to MEK/ERK blockade could be restored by inhibition of Stat3, which is constitutively activated in human melanoma and contributes to cell growth and survival." (PMID 24920406, 2014). "Finally, we evaluated the effect of STAT3 silencing on the biological behavior of melanoma cells." (PMID 24344100, 2013). "Similar to the RAS/BRAF/MAPK signaling activation, down-regulation of STAT3 by lentiviral shRNA in STAT3-activated melanoma resulted in inhibition of multiple immunosuppressive cytokines, including IL-6, IL-10, and VEGF, indicating that STAT3 inhibitors may also be useful for immunotherapy." (PMID 23755373, 2013). "STAT3 is constitutively activated in numerous cancer cell lines and in many solid and hematological human cancers, including multiple myeloma, several lymphomas and leukemias, breast cancer, prostate cancer, ovarian carcinoma, melanoma, renal carcinoma, and colorectal carcinoma." (PMID 23950841, 2013). "We sought to determine whether the increased expression of p-STAT3 in non-CNS systemic melanoma metastasis is associated with an increased risk of developing CNS metastasis and is a negative prognostic factor for overall survival time." (PMID 22488042, 2012). "Furthermore, M2 macrophages defined by their expression of p-STAT3 have also been shown to support angiogenesis and growth in melanoma and may also be a prognostic factor in melanoma patients." (PMID 22488042, 2012). "Therefore, down-regulation of Mcl-1 by inhibition of phosphorylated STAT3 may be an important mechanism of action of SOID-8 in these melanoma cells." (PMID 23166634, 2012). "Importantly, STAT3 is also sensitive to inhibition by SOCS proteins and prior studies in melanoma brain metastases have suggested that loss of SOCS1 expression could promote metastasis via elevated STAT3 signaling." (PMID 20398276, 2010). "Melanoma-derived exosomal miR-155 downregulates suppressor of cytokine signaling 1 (SOCS1), an inhibitor of the JAK2/STAT3 pathway, activating JAK2/STAT3 signaling, promoting MMP-9 expression, and enhancing tumor angiogenesis." (PMID 40284474, 2025).
melanoma (continued). "Our study showed that inhibition of STAT3 proficiently reduced COX-2 expression both alone and induced by IFN-γ in melanoma, consistent with previous reports of STAT3 occupying and regulating expression at the COX-2 promoter." (PMID 39941844, 2025). "Hyperactivation of STAT3 is crucial for the invasion and metastasis of skin cancers, including SCC, BCC and melanoma." (PMID 40399946, 2025). "Cisplatin represses MDSCs expansion by suppressing STAT3/COX-2 signaling and enhances T-cell responses in melanoma and HNSCC patients." (PMID 40612857, 2025). "Blocking STAT3 or SRC signaling decreases key cell survival proteins, including Bcl-xL and Mcl-1 (Myeloid cell leukemia-1), precipitating apoptosis in melanoma cells." (PMID 40399946, 2025). "Reiko's findings suggest that the overexpression of ZIC5 can enhance the invasiveness of melanoma primarily by activating the FAK and STAT3 signalling pathways." (PMID 40344305, 2025). "ZBED3-AS1 links the STAT3 pathway with the PI3K–Akt signalling cascade, which is involved in oncogenesis, including the biology of melanoma." (PMID 41463281, 2025). "FAK also modulates E-cadherin levels via Src.c/ERK1/2/Stat3 and PPAR/Stat3 signaling in B16F10 cell and human melanoma cell lines." (PMID 41373571, 2025). "In a nutshell, our results demonstrate that DHT targets STAT3 and suppresses the STAT3/SOX2 signaling pathway to reduce the activity of BRAF mutant melanoma cells." (PMID 39944829, 2025). "In melanoma, NR2F1-AS1 is transcriptionally activated by STAT3 and drives proliferation by repressing miR-493-5p and enhancing GOLM1." (PMID 40828427, 2025). "In melanoma, PAI-1 promotes PD-L1 expression in both tumor cells and stromal cells via the JAK1/STAT3 pathway." (PMID 41008624, 2025). "Beyond melanoma, PAI-1 facilitates tumor progression in other cancers by promoting M2 polarization through JAK2/STAT3 signaling." (PMID 41008624, 2025). "Put differently, the conjunction of DHT and BRAF/MEK inhibitors can effectively block the pathways of STAT3/SOX2 and MAPK, decrease the growth and spread of drug-resistant primary melanoma cells, and promote apoptosis." (PMID 39944829, 2025). "In human melanoma cells, inhibition of GLI1 expression prevented the induction of IDO1 expression in response to IL6/STAT3 and IFNγ/STAT1 signaling." (PMID 39962447, 2025). "Mutations in DDX3X also correlate with increased phosphorylation of STAT3 and p42/p44 MAPK, contributing to chemoresistance in melanoma." (PMID 39823244, 2025). "In BRAFV600E-positive human melanoma, activation of the JAK2/STAT3 pathway led to increased COX-2 expression, sustaining chronic inflammation and promoting tumor evasion." (PMID 39941844, 2025). "In NSCLC, high tumor-infiltrating Th1 cells correlate with poor prognosis, whereas Th17 dominance in melanoma and CRC promotes immunosuppression through IL-6/STAT3 signaling and regulatory T cell (Treg) conversion." (PMID 40564985, 2025). "Mechanistically, in melanoma cells, the CCNB1/CDK1 complex phosphorylates STAT3, activating the IL-6/STAT3 positive feedback loop, which upregulates PD-L1 and enables resistance to NK cell-mediated cytotoxicity." (PMID 40430484, 2025). "Mechanistic studies revealed that signal transducer and activator of transcription 3 (STAT3) phosphorylation was repressed by VA treatment, which was confirmed in a cell model of adipocyte conditioned medium-treated B16BL6 melanoma cells." (PMID 40563342, 2025). "In melanoma cells (SK-MEL-2 and A375), STAT3-mediated upregulation of NR2F1-AS1 leads to the activation of the miR-493-5p/GOLM1 axis, thereby promoting invasion and migration." (PMID 40828427, 2025). "Quercetin, in turn, was demonstrated to reduce melanoma cells migration through inhibition of FAK-paxillin-Akt expression and the STAT3 signaling pathway." (PMID 40364408, 2025). "However, STAT3 activation in brain metastases might foster brain colonization of melanoma cells." (PMID 38386085, 2024).
melanoma (continued). "In the present study, STAT3, as a transcription factor, binds to enh17 to regulate the expression of ETV4, thereby inducing cell proliferation and migration in melanoma cells." (PMID 38849954, 2024). "We performed iterative simulations modifying the values of E2F1 expression and found, that under basal STAT3 activation, increasing levels of E2F1 in melanoma cells can trigger the expression and secretion of IL-6." (PMID 39544930, 2024). "In melanoma cells, there is an elevated expression of KCNQ1OT1, which affects the miR-34a/STAT3 pathway, leading to the enhancement of expansion, migration, and aggression capabilities." (PMID 38462628, 2024). "STAT3 antagonizes MITF and drives melanoma metastasis in vivo suggesting a potential STAT3-mediated dedifferentiation in response to GRASLND downregulation." (PMID 39398277, 2024). "STAT3 siRNA and IM in combination showed greater inhibition of STAT3 protein expression, decreased cell viability, and increased apoptotic activity in B16F10 melanoma cells." (PMID 38831883, 2024). "B16 mouse melanoma tumor cells and DU145 prostate cancer cells, showed high STAT3 activity by increasing phosphorylation of RelA protein in the presence of TNF-α." (PMID 38571491, 2024). "Another publication shows that silencing STAT3 via peptidomimetic lipid nanoparticles (LNP)-mediated systemic delivery of RNAi downregulated PD-L1, resulting in the inhibition of melanoma growth." (PMID 39618825, 2024). "Previous studies have demonstrated that IFNγ-induced PD-L1 expression is reliant on JAK1/JAK2 activity, and that PD-L1 promoter activity and subsequent expression is mainly influenced by STAT1/STAT3 and IRF1 in IFNγ treated melanoma cells." (PMID 39736644, 2024). "Meanwhile, a correlation between IL-6 levels, phosphorylated STAT3 and CCR5 expression in tumor-infiltrating MDSC was confirmed in a RET transgenic melanoma mouse model." (PMID 38952546, 2024). "Consistently, the clinical data revealed that melanoma with abundant E2F1, STAT3 and IL-6 preferentially induce and maintain infiltration of Th2, while simultaneously blocking Th1 cells." (PMID 39544930, 2024). "Our simulations suggest that high levels of IL-6 secretion by melanoma cells can be either achieved through high levels of E2F1, high levels of STAT3, or moderate levels of both TFs." (PMID 39544930, 2024). "Other transcriptional factors involved in PD-L1 regulation in melanoma include MYC, hypoxia-inducible factor-1α and 2α (HIF-1α/2α), STAT3 and NF-κB." (PMID 38633217, 2024). "ERK5 activation in macrophages leads to the phosphorylation of signal transducer and activator of transcription 3 (STAT3), thus promoting melanoma growth." (PMID 38785963, 2024). "Transcription factor STAT3 was found to bind to the enh17 region to promote the expression of ETV4, which ultimately contributes to promoting tumor progression in melanoma." (PMID 38849954, 2024). "STAT3 was clearly recovered from E2F1 immunoprecipitates of whole melanoma cell lysates, whereas knockdown of E2F1 resulted in decreased binding of STAT3." (PMID 39544930, 2024). "WP1066 reduced IL-6-induced p-STAT3 expression and enhanced CD3+ T cell cytotoxicity against melanoma." (PMID 37741983, 2023). "We next tested the effect of IL-6/JAK/STAT3 pathway inhibition on the ability of YDFR.CB3 and DP.CB2 melanoma cells to form spheroids with microglia cells." (PMID 37296634, 2023). "In order to identify the melanoma-derived factor(s) that induce STAT3 phosphorylation and SOCS3 upregulation, we fractionated the MCM from the four different melanoma cell lines to extracellular vesicles (EVs) and soluble fraction (SF or MCM depleted of EVs)." (PMID 37296634, 2023). "Microglia cells showed significantly higher mRNA expression for JAK1, STAT3, and SOCS3 compared to melanoma cells." (PMID 37296634, 2023).